GFM2 (GTP dependent ribosome recycling factor mitochondrial 2)
Description:
Mitochondrial GTPase that mediates the disassembly of ribosomes from messenger RNA at the termination of mitochondrial protein biosynthesis. Acts in collaboration with MRRF. Promotes mitochondrial ribosome recycling by dissolution of intersubunit contacts. GTP hydrolysis follows the ribosome disassembly and probably occurs on the ribosome large subunit. Not involved in the GTP-dependent ribosomal translocation step during translation elongation.
Synonyms: RRF2mt; EF-G2mt; mEF-G 2; hEFG2; EFG2; MSTP027; FLJ21661; MRRF2; MST027; RRF; RRF2
Tractability: Small molecule: a structure with a bound ligand is known. PROTAC: ubiquitination databases record sites on it; its protein half-life has been measured.
Gene: Protein-coding gene on chromosome 5 (74,721,206 to 74,767,147, reverse strand). Ensembl gene ENSG00000164347.
Subcellular location: Mitochondrion
Subcellular location (Human Protein Atlas): Mitochondria; Midbody ring; Nucleoplasm
Pathways (Reactome):
Metabolism of proteins: Mitochondrial translation termination
Gene Ontology:
Molecular function: GTPase activity; protein binding; translation elongation factor activity; GTP binding
Biological process: mitochondrial translation; mitochondrial translational elongation; ribosome disassembly; mitochondrial translational termination; translation
Cellular component: mitochondrion; mitochondrial matrix
Genetic constraint (gnomAD): Loss-of-function variants: 37 observed, 45.65 expected, observed/expected ratio (o/e) 0.81, 90% interval 0.62 to 1.07. The upper end of that interval is the gene's LOEUF score, 1.07, which puts it in group 4 of 6, group 1 being the genes least tolerant of losing a copy. Missense variants: 475 observed, 562.69 expected, observed/expected ratio (o/e) 0.84, 90% interval 0.78 to 0.91. Synonymous variants: 166 observed, 205.22 expected, observed/expected ratio (o/e) 0.81, 90% interval 0.71 to 0.92.
Gene-disease validity (ClinGen):
ClinGen rates the evidence that GFM2 causes each of these diseases.
Leigh syndrome (autosomal recessive): Moderate. A progressive neurological disease defined by specific neuropathological features associating brainstem and basal ganglia lesions.
Homologues: Orthologues: chimpanzee GFM2 (99% identical), macaque GFM2 (97% identical), pig GFM2 (91% identical), dog GFM2 (90% identical), rabbit GFM2 (88% identical), guinea pig GFM2 (87% identical), mouse Gfm2 (84% identical), rat Gfm2 (84% identical), tropical clawed frog gfm2 (70% identical), zebrafish gfm2 (65% identical), Drosophila melanogaster mRRF2 (39% identical), Caenorhabditis elegans Y119D3B.14 (35% identical). Paralogues in human: GFM1 (33% identical), EFL1 (21% identical), EEF2 (21% identical), EFTUD2 (20% identical), GUF1 (14% identical), MTIF2 (12% identical), EEF1A1 (12% identical), EEF1A2 (12% identical), EEFSEC (12% identical), TUFM (11% identical), HBS1L (11% identical), GSPT1 (9% identical), and 6 more.
Diseases named in the same sentence as GFM2 in open-access papers:
GFM2 is named in the same sentence as 16 diseases in open-access papers, as found by Europe PMC text mining. Sharing a sentence is not in itself a finding about the gene and the disease. The quoted sentences say what the papers report.
breast carcinoma (2 papers, 2019 to 2023). "Little is known about this protein in the context of breast cancer, but genomic mutation and loss of GFM2 associates with impaired mitochondrial respiration in muscle." (PMID 37608351, 2023). "Analyzing all tumor subtypes together suggested that the alterations in expression of glycolytic (SLC16A3)- and mitochondrial (GFM2)-associated genes may be a general feature of aggressive breast cancers." (PMID 37608351, 2023).
Leigh syndrome (2 papers, 2017 to 2021). "Two families with gene defects in GFM2, identified through whole exome sequencing, have previously been described in the literature associated with Leigh syndrome, microcephaly, simplified brain gyral pattern and insulin-dependent diabetes." (PMID 29075935, 2017). "Mutations in GFM2 have been found in patients with Leigh syndrome." (PMID 34277617, 2021). "Thus, the GFM2 mutation may be the cause of Leigh syndrome with multiple congenital arthritis phenotypes." (PMID 34277617, 2021). "To date, GFM2 variants have been identified in four patients (two sets of siblings), with phenotypes described as microcephaly, simplified gyral pattern and insulin-dependent diabetes in the first report and Leigh syndrome complicated by arthrogryposis multiplex congenita in the most recent family." (PMID 29075935, 2017).
chronic kidney disease (1 paper, 2024). Impairment of the renal function secondary to chronic kidney damage persisting for three or more months. "In the current paper, we show that NSA2 expression is co-regulated with the GTP-dependent ribosome recycling factor mitochondrial 2 (GFM2) and provide a molecular link between cytosolic and mitochondrial ribosomal biogenesis with mitochondrial dysfunction in chronic kidney disease (CKD)." (PMID 39396937, 2024).
developmental delay (1 paper, 2017). "In summary, we present two patients with developmental delay, dystonia, dysarthria and neuroimaging abnormalities in the putamen and caudate nuclei, along with subcortical white matter involvement who harbour previously unreported GFM2 variants, identified through the application of WES." (PMID 29075935, 2017).
diabetes (1 paper, 2024). "The demonstration that GFM2 upregulation achieved by transfection increased certain OXPHOS complexes and reduced mitochondrial respiration suggests that in diabetes, the detrimental effect on mitochondrial function could be directly caused by the increase of GFM2." (PMID 39396937, 2024). "Our results demonstrate that GFM2 upregulation contributes to hyperglycaemia-induced mitochondrial dysfunction in renal tubular cells in diabetes." (PMID 39396937, 2024).
fumaric aciduria (1 paper, 2023).
hyperglycaemia (1 paper, 2024). "The reduction of mitochondrial respiration parameters with increased OXPHOS proteins caused by GFM2 upregulation suggests that in diabetic renal cells, hyperglycaemia-induced mitochondrial dysfunction may result from dysregulated ribosome functions in cytosol and mitochondria." (PMID 39396937, 2024). "Alternatively, it maybe that oxidative stress or related pathways resulting from hyperglycemia initiate the change in GFM2 which then is one of several mechanisms contributing to mitochondrial dysfunction." (PMID 39396937, 2024). "Furthermore, increased GFM2 expression, via transient transfection or hyperglycemia, correlated with decrease cellular respiration." (PMID 39396937, 2024). "Sixthly, we showed that inducing over expression of GFM2 in the absence of hyperglycaemia also caused similar changes to those under hyperglycaemic conditions, providing support for the view that GFM2 over expression rather than hyperglycaemia per se may be causative of mitochondrial dysfunction." (PMID 39396937, 2024).
mitochondrial disease (3 papers, 2017 to 2025). "Diseases associated with GFM2 included combined oxidative phosphorylation deficiency 39 and mitochondrial metabolism disease." (PMID 32776492, 2020). "Among these genes, the variants of elongation factors TUFM, TSFM, GFM1, and GFM2 were reported to be associated with mitochondrial diseases, mainly causing oxidative phosphorylation deficiency diseases." (PMID 32776492, 2020). "Through the application of whole exome sequencing, we have identified previously unpublished recessive GFM2 variants in two unrelated patients with clinical features of mitochondrial disease and biochemical evidence of respiratory chain dysfunction." (PMID 29075935, 2017). "Here we present two unrelated patients with previously unreported variants in GFM2, documenting OXPHOS deficiencies in different tissues and expanding the clinical phenotypes associated with GFM2-related mitochondrial disease." (PMID 29075935, 2017). "The histochemical, biochemical and genetic investigations, together with the functional data presented in this report, form compelling evidence that the GFM2 variants identified through WES are pathogenic and causative of mitochondrial disease in both patients." (PMID 29075935, 2017).
renal disease (1 paper, 2024). "A final limitation is that the direction causality of elevated GFM2 and mitochondrial dysfunction needs confirmation, as this would provide an important step in the pathway of renal disease." (PMID 39396937, 2024). "Our data link the regulation of 2 highly conserved genes, NSA2 and GFM2, connected to ribosomes in two different cellular compartments, cytosol and mitochondria, to kidney disease and shows that their dysregulation may be involved in mitochondrial dysfunction." (PMID 39396937, 2024).
GFM2 also shares sentences with these, for which no sentence is quoted: tumor (2 papers); arthrogryposis multiplex congenita (1); COVID-19 (1); Dystonia (1); insulin-dependent diabetes (1); microcephaly (1); rhabdomyosarcoma (1).